FOXO1 (forkhead box O1)
Diseases named in the same sentence as FOXO1 in open-access papers (continued):
Sharing a sentence is not in itself a finding about the gene and the disease.
Stroke (10 papers, 2013 to 2026). Sudden impairment of blood flow to a part of the brain due to occlusion or rupture of an artery to the brain. "Overexpression of PRAS40 can promote phosphorylation of Akt/FoxO1 with inhibition of FoxO1 activity, and it can be associated with reduced infarction size in rats that undergo stroke." (PMID 35371601, 2022). "During a stroke, modifications of FoxO1 have been linked to a variety of functions, such as inducing cell death and inflammation, inhibiting oxidative injury, affecting the blood brain barrier (BBB), and regulating hepatic gluconeogenesis." (PMID 35371601, 2022). "The PI3K/Akt/Foxo1 pathway is involved in the neuroinflammation caused by a stroke." (PMID 35163437, 2022). "After a stroke, the dephosphorylation of FoxO1 causes apoptosis through the Akt pathway." (PMID 35371601, 2022). "Strokes are caused by the occlusion of major cerebral arteries, leading to widespread tissue damage, which may be associated with the FoxO1 activity." (PMID 35371601, 2022). "In agreement with previous results, we saw a higher level of FoxO1 expression in the cytoplasm compared to the nucleus after exercise post‐conditioning, suggesting that this exercise intervention deactivated FoxO1 after stroke." (PMID 36448290, 2023). "In this study, PostE reduced brain injury after stroke, in association with activated PI3K/AKT/FoxO1 signals and inhibited gluconeogenesis." (PMID 36448290, 2023). "In this study, PostE reduced brain injury after stroke, in association with activated PI3K/AKT/FoxO1 signaling, and inhibited gluconeogenesis." (PMID 36448290, 2023). "The data suggest that PostE decreased post‐stroke gluconeogenesis by activating phosphorylation of PI3K/AKT/FoxO1 signaling." (PMID 36448290, 2023). "In conclusion, the roles of FoxO1 within the full spectrum of stroke, as well as the subtle regulation and application mechanism of FoxO1, are waiting to be studied and defined." (PMID 35371601, 2022). "It proved that Pic potentially exerts neuroprotective effects through upregulation of Sirt1/FoxO1 signaling in stroke." (PMID 36105479, 2022). "The major post-translational modifications that are studied on FoxO1 after stroke are acetylation and phosphorylation." (PMID 35371601, 2022). "This review will discuss all of the significant pathways in which FoxO1 plays an important role during stroke damage and recovery." (PMID 35371601, 2022). "There was a dose-dependent increase in antioxidant activity and suppression of apoptosis with Pic, as well as upregulation of Sirt1/FoxO1 signaling in stroke." (PMID 36105479, 2022). "There are many ways that FoxO1 induces apoptosis, which ultimately contributes to the pathogenesis of strokes." (PMID 35371601, 2022). "Overall, the functions of FoxO1 are multifactorial, and this paper will summarize all of the significant pathways in which FoxO1 plays an important role during stroke damage and recovery." (PMID 35371601, 2022). "In addition, signaling pathway inhibitors and activators or FOXO1 gene knockdown were used to clarify the function of the PI3K/AKT signaling pathway and FOXO1 in Gypenoside XLIX protection against stroke." (PMID 40918528, 2025). "The findings suggest that Gypenoside XLIX may promote mitochondrial autophagy in neuronal cells and reduce intracellular ROS accumulation by regulating the PI3K/AKT/FOXO1 signaling pathway, which could potentially alleviate stroke-related damage." (PMID 40918528, 2025). "The role of FoxO1 on its target factors implies that if we could clearly clarify its regulatory activity, the FoxO1 might be a new optimized pathway of targeted stroke therapy." (PMID 35371601, 2022). "Besides phosphorylation, FoxO1 undergoes additional post-translational modifications after stroke such as acetylation." (PMID 35371601, 2022). "Whether PP2A or other pathways could dephosphorylate FoxO1 after stroke needs to be further studied." (PMID 35371601, 2022).
Stroke (continued). "However, the subtle mechanisms of post-transcriptional modification and the role of FoxO1 are still elusive and even contradictory in the development of stroke." (PMID 35371601, 2022). "FoxO1 plays a major role in brain damage following a stroke." (PMID 35371601, 2022). "Different interventions targeting FoxO1 after stroke have achieved different effects." (PMID 35371601, 2022). "Currently, the role FoxO1 plays in stroke damage will be assessed." (PMID 35371601, 2022). "Furthermore, FoxO1 can act as a tumor suppressor and thus activating FoxO1 may help treat certain cancers, yet FoxO1 activation worsens stroke pathology." (PMID 37941908, 2023). "In summary, we demonstrated a neuroprotective effect of PostE after stroke due to its reduction of gluconeogenesis levels and modulation of PI3K/AKT/FoxO1 signaling." (PMID 36448290, 2023). "Moreover, the specific regulation methods of FoxO1 are still unknown in the stroke period." (PMID 35371601, 2022). "Silencing of the transcription factor Forkhead box O1 (FoxO1) via the lncRNA GAS5/miR-378a-5p/Hspa5 axis in mice significantly improved neurological function recovery in intracerebral hemorrhage, which is the most devastating stroke subtype." (PMID 37987360, 2023). "FoxO1 has been shown to be involved in the regulation of apoptosis, anti-oxidative stress, BBB disruption, hepatic gluconeogenesis and inflammation during the pathophysiological processes of stroke." (PMID 35371601, 2022). "Of note, Akt is the primary upstream kinase in FoxO1 signaling transduction pathway regulation and is a negative regulator of FoxO1, including after a stroke." (PMID 35371601, 2022). "The balance betwwen the intracellular transcriptional activity of FoxO1 and its regulators is critical to stroke progression, even though its mechanism has not yet been fully established." (PMID 35371601, 2022). "It is not clear whether all the targets of FoxO1 are modulated during stroke." (PMID 35371601, 2022).
hypertriglyceridemia (9 papers, 2014 to 2024). A laboratory test result indicating elevated triglyceride concentration in the blood. "Hepatic FoxO1, associated with insulin resistance, plays a crucial role in impairing ApoC3 production and contributing to hypertriglyceridemia in obese mice." (PMID 38441531, 2024). "Moreover, FoxO1 knockdown rescued the diabetic phenotype in insulin-resistant mice, whereas constitutive activation of FoxO1 caused hyperglyceridemia and impaired insulin secretion." (PMID 28349071, 2017). "Another investigation reported FoxO1’s involvement in VLDL production and associated TG in the liver, influencing hypertriglyceridemia by modulating the microsomal TG transfer protein (MTP) in mice." (PMID 38441531, 2024). "In the present study, AS treatment reduced diabetic plasma triglyceride, implicating that FOXO1 may contribute to hypertriglyceridaemia in T1DM." (PMID 32450616, 2020). "However, whether activated FOXO1 in the liver augments the apolipoprotein expression and thus contributes to hypertriglyceridaemia in T1DM merits further investigation." (PMID 32450616, 2020). "In a study of a high-fructose fed hamster, Foxo1 localized in the nucleus of hepatocytes induced overexpression of apoC-III and hypertriglyceridemia." (PMID 32182991, 2020). "We show leucine-dependent accumulation of FOXO1, which promotes transcription of microsomal TG transfer protein (MTP) and VLDL production and leading to hepatic hypertriglyceridemia." (PMID 25859286, 2014). "Additionally, it was shown that activated FOXO1 induced SREBP-1 and very low-density lipoprotein (VLDL) expression and promoted hypertriglyceridemia through modulation of microsomal TG transfer protein (MTP)." (PMID 39736705, 2024).
liver disease (9 papers, 2022 to 2025). "Furthermore, the expression levels of miR-182-5p, Cyld and Foxo1 detected in liver human samples by using GSE22058 datasets evidenced the miR-182-5p expression increase in hepatic disease progression associated with a concurrent Cyld/Foxo1 level decrease." (PMID 37298191, 2023). "The intrahepatic expression of FoxO1 could have clinical utility as a potential prognostic marker for patients with advanced liver disease." (PMID 38075169, 2023). "In addition, signalling pathways such as Akt/FoxO1, AMPK, PPAR γ, Smad2/3 and Caspase-3 have been shown to be vital molecular targets for FA involvement in improving various liver diseases." (PMID 37324465, 2023).
Cognitive impairment (8 papers, 2018 to 2025). Abnormal cognition is characterized by deficits in thinking, reasoning, or remembering. "Our study suggests that EA‐induced activation of the SIRT1/FOXO1 autophagy signalling pathway and oxidative stress are involved in ameliorating postoperative cognitive impairment." (PMID 40008520, 2025). "miR-181a negatively targets forkhead box protein O1 (FOXO1), decreasing amyloid plaque deposition in the hippocampus and cortex, mitigating pericyte loss and BBB disruption in APP/PS1 mice, and ameliorating cognitive impairment in mice." (PMID 36291714, 2022). "Administration of domoic acid in mice can induce cognitive deficits associated with mitochondrial dysfunction which was shown to be ameliorated by UA via modulation of the PI3K/Akt and forkhead box protein O1 (FoxO1) signalling pathways." (PMID 31223427, 2019). "Additionally, exercise, an AD intervention, increases circulating FoxO1 in African American men with mild cognitive impairment, and upregulates FoxO1 to improve AD symptoms in early-onset AD mice." (PMID 37941908, 2023). "In addition, SIRT1/FOXO1 signalling may be involved in cognitive impairment by regulating autophagy." (PMID 40008520, 2025). "Second, we could not verify the specificity of the neuronal activity and AKT/FOXO1/HO-1 signaling changes to the negative emotions and cognitive deficits." (PMID 40565203, 2025). "First, we only investigated the neuronal activity and AKT/FOXO1/HO-1 expression in two representative brain regions (the PFC and CPu) in METH withdrawal-induced negative emotions and cognitive deficits." (PMID 40565203, 2025). "Thus, we hypothesize that the AKT/FOXO1/HO-1 signaling pathway in the PFC and CPu may play a role in METH withdrawal-induced negative emotions and cognitive deficits." (PMID 40565203, 2025).
esophageal cancer (8 papers, 2015 to 2025). A primary or metastatic malignant neoplasm involving the esophagus. "As the upstream regulator of OTUD3, we found that nuclear FOXO1 expression positively correlated with OTUD3 expression in esophageal cancer tissues and was significantly associated with the smoking behavior of patients." (PMID 34853315, 2021). "In summary, our study shows that increased FOXO1 immunostaining is marginally linked to aggressive tumor features in esophageal cancer but is unrelated to survival of patients." (PMID 30478420, 2018). "Our data demonstrate that FOXO1 overexpression and loss of pSerine256-FOXO1 expression are linked to a subset of esophageal cancers with aggressive tumor features." (PMID 30478420, 2018). "In this study, we identified FOXO1, known to be involved in key signaling pathways, as an additional deregulated marker linked to prognosis of patients with esophageal cancers." (PMID 30478420, 2018). "This study was performed to get more insights in the prognostic relevance of Forkhead box O 1 (FOXO1) and pSerine256-FOXO1 in esophageal cancers." (PMID 30478420, 2018). "The function of Forkhead box O 1 (FOXO1) and pSerine256-FOXO1 immunostaining in esophageal cancer is unclear." (PMID 30478420, 2018). "To gain more insights in the potential clinical utility of FOXO1 and pSerine256-FOXO1 protein analysis in esophageal cancer, we used our tissue microarray of more than 600 esophageal cancer specimens with clinical follow-up data." (PMID 30478420, 2018). "Interestingly, FoxO1 overexpression in esophageal cancer promotes tumor development by increasing macrophage infiltration." (PMID 34539243, 2021). "Here, we analyzed FOXO1 and pSerine256-FOXO1 expression in esophageal cancers." (PMID 30478420, 2018). "However, the prevalence and clinical significance of FOXO1 and pSerine256-FOXO1 expression in esophageal cancer remains elusive." (PMID 30478420, 2018). "Specifically, nicotine activated the PI3K/AKT signaling through the alpha 7 nAChR to inhibit FOXO1 activity and downregulate OTUD3 expression, leading to inhibition of VEGF-C mRNA decay and increase of VEGF-C paracrine secretion in esophageal cancer cells." (PMID 34853315, 2021). "However, our data suggests that FOXO1 might play an oncogenic role in esophageal cancers." (PMID 30478420, 2018). "For instance, FOXO1 promotes macrophage recruitment and M2-like macrophage polarization by enhancing the secretion of CSF-1 (colony-stimulating factor 1) and CCL20 (chemokine ligand 20) in esophageal cancer." (PMID 38714539, 2024).
ischemic heart disease (8 papers, 2014 to 2024). "This combined approach of bioinformatics and experimental validation has allowed the identification of CCR7 and FOXO1 transcripts as miRNA-regulated, Oxstress intermediates of coronary arterial disease." (PMID 32178422, 2020). "In addition, coronary artery disease can lead to the activation of the SIRT1/FoxO1 signaling pathway and activation of the apoptotic signaling pathway, and safflower can reverse this result." (PMID 35607519, 2022). "In general, FOXO1 has been found to play a protective role in ischemic heart diseases." (PMID 26956801, 2016).
COVID-19 (7 papers, 2020 to 2024). A disease caused by infection with severe acute respiratory syndrome coronavirus 2. "Here authors show in a mouse model of SARS-CoV-2 infection that IL-9, predominantly produced by helper T cells, plays a critical pathogenic role in COVID-19 via an inflammatory pathway involving the transcription factor Foxo1." (PMID 37429848, 2023). "We observed that Foxo1 and IL-9 expression is increased in active human Covid19 patients, and in the lungs of SARS-CoV-2-infected hamster and ACE2.Tg mice, suggesting that Foxo1-IL-9 axis might be critical for SARS-CoV-2 infection and lung inflammation." (PMID 37429848, 2023). "If targeting FoxO1 is considered as a therapeutic approach for COVID-19, assessing hsa-miR-223-3p and hsa-miR-15b-5p levels becomes crucial." (PMID 39203974, 2024). "Expression of hsa-miR-132 target genes, such as MAPK1, and FOXO1, involved in neuroinflammation or neuroprotective mechanisms, respectively, was found to be affected in COVID-19 patients." (PMID 37008787, 2023). "We show that Foxo1-IL-9 axis controls two distinctive pathological features that critically contribute to the progression and severity of COVID-19 - namely anti-viral pathway and airway inflammation." (PMID 37429848, 2023). "Exogenous IL-9 increases airway inflammation in Foxo1-deficient mice, while IL-9 blockade reduces and suppresses airway inflammation in SARS-CoV-2 infection, providing further evidence for a Foxo1-Il-9 mediated Th cell-specific pathway playing a role in COVID-19." (PMID 37429848, 2023). "Altogether, we identified one of the key mechanisms of T cell-mediated immunopathology in Covid19 by showing that Foxo1 and IL-9 controls two distinctive pathological features that critically contribute to the progression and severity of COVID-19—namely anti-viral pathway and airway inflammation." (PMID 37429848, 2023).
diabetic retinopathy (7 papers, 2010 to 2024). "FoxO1 knockdown by siRNA prevents the loss of microvascular endothelial cells in the retina and pericytes, which constitutes the first step in diabetic retinopathy." (PMID 33804729, 2021). "Knockdown of FOXO1 by siRNA in vivo diminishes the loss of retinal microvascular endothelial cells and pericytes, the first step in diabetic retinopathy." (PMID 24864265, 2014). "Thus, the protective effect of the HMGA1 rs139876191 variant on diabetic retinopathy may also be mediated through a process that involves inactivation of FoxO1 gene and protein expression." (PMID 29052178, 2018). "FoxO1 activation is elevated in patients suffering from diabetic retinopathy by enhancing apoptotic processes in pericytes and microvascular endothelial cells." (PMID 33804729, 2021). "In this context, the involvement of FoxO1 in the induction of genes involved in diabetic retinopathy and its activation during the early inflammatory phase of diabetic retinopathy has been reported." (PMID 29052178, 2018). "FOXO1 promotes diabetic retinopathy by increasing apoptosis in microvascular endothelial cells and pericytes." (PMID 24864265, 2014). "In vitro TNF-α and an advanced glycation end-product, which are elevated in diabetic retinopathy, induce pericyte apoptosis through activation of the transcription factor FOXO1." (PMID 24864265, 2014). "Therefore, we suggest that the elevation of FOXO1 in addition to other effects can play a role in the pathogenesis of diabetic retinopathy through apoptosis of pericytes." (PMID 20300563, 2010). "Thus, studies presented here indicate AGEs and TNF-α could contribute to diabetic retinopathy through FOXO1-mediated pericyte apoptosis." (PMID 20300563, 2010). "FOXO1 may exert a pro-apoptotic function in pericytes in diabetic retinopathy based on the observation that cultured bovine retinal pericytes stimulated with TNFα or AGE products exhibited FoxO1-dependent apoptosis and that FOXO1 RNA interference lowered retinal pericyte apoptosis in diabetic rats." (PMID 32117997, 2020).
fibrosis (7 papers, 2019 to 2025). the formation of excess fibrous connective tissue in an organ or tissue in a reparative or reactive process. "Collectively, our data demonstrated that HMGA1 plays a critical role in the development of cardiac fibrosis by regulating FOXO1 transcription." (PMID 34513822, 2021). "In the physiological aging process in mice, 12-week NAC treatment ameliorated aortic fibrosis possibly by stimulating M2 macrophage polarization, and SIRT1, SIRT3 and FOXO1 may play a role in unidentified pathways linking vascular oxidative stress to fibrosis associated with aging." (PMID 34530696, 2021).
glucose metabolism disorders (7 papers, 2016 to 2025). "Collectively, these data indicate that FoxO1 mediates myocardin downregulation-induced lipid and glucose metabolism disorders." (PMID 38505620, 2024). "ameliorates insulin sensitivity and glucose metabolism disorders by regulating the IRS1/PI3K/AKT signaling pathway and the expressions of its downstream targets GLUT4, FOXO1, and GSK3β." (PMID 40351361, 2025).
lipid metabolism disorders (7 papers, 2014 to 2025). "The conserved transcription factor Forkhead box protein O1 (FoxO1) was reported to ameliorate lipid metabolism disorders in obese population." (PMID 39135158, 2024). "Our study confirms the important regulatory role of FoxO1 in stress-induced lipid metabolism disorders." (PMID 31579588, 2019). "Akt promotes translocation of FOXO1 from the nucleus to the cytoplasm, consequently, liver gluconeogenesis was inhibited, and lipid metabolic disorder and oxidative activation were attenuated." (PMID 25140191, 2014). "Our previous experiments found that FoxO1 may be involved in stress-induced lipid metabolism disorders." (PMID 31579588, 2019). "Our study demonstrated that lncRNA MEG3 regulates de novo lipogenesis by decreasing the expression and nucleus translocation of FOXO1 in HepG2 cells, suggesting that lncRNA MEG3 could be a promising therapeutic target in lipid metabolic disorders." (PMID 38713402, 2024). "CJE could inhibit gluconeogenesis and promote glycogen synthesis through the insulin-mediated IRS1-PI3K-Akt-FoxO1/GSK 3β pathway and increase glucose transport through the AMPK-GLUT4 pathway, thereby regulating glucose and lipid metabolism disorders in T2DM mice." (PMID 40077469, 2025).